EPCAM (epithelial cell adhesion molecule)
Diseases named in the same sentence as EPCAM in open-access papers (continued):
Sharing a sentence is not in itself a finding about the gene and the disease.
breast carcinoma (continued). "Based on our previous analysis of EpCAM expression in epithelium- and mesenchyme-like breast carcinoma cell lines we selected three EpCAMhigh cell lines for lentiviral knockdown studies, i.e. T47D with a strongly glycosylated, MCF-7 with basic and glycosylated, SkBR-3 with only basic EpCAM isoform." (PMID 23110550, 2012). "The change in circulating epithelial tumor cells (CETC) was monitored in 66 breast cancer patients operated on with breast conserving surgery or mastectomy and during the further course of the disease, analyzing CETC from unseparated white blood cells stained with FITC-anti-EpCAM." (PMID 24212822, 2011). "However, only minimal changes in cell cycle and proliferation (data not shown) were observed following specific ablation of EpCAM expression in MDA-231 breast cancer cells under these experimental conditions." (PMID 22132731, 2011). "Since the majority of breast cancer cell lines failed to maintain EpCAM+/CD24+/CD49f- Luminal 1 cells in vitro, we wanted to determine whether this was a general feature of in vitro cell cultivation or was a consequence of malignancy." (PMID 20964822, 2010). "In addition, it was found that EpCAM, a tumour associated antigen, up-regulates E-FABP and furthermore that EpCAM is positively correlated with the grade of dysplasia being a negative prognostic factor for breast cancer patients." (PMID 18544163, 2008). "However, albeit rather rarely observed in breast cancer, not all CTCs show EpCAM expression, either because they might have undergone epithelial‐to‐mesenchymal transition (EMT) or because of their tissue origin." (PMID 41144783, 2026). "Indeed, EMP2 and PPIC transcripts in spiked blood samples indicated the presence of Hs579T breast cancer cells; in contrast, the analysis of the epithelial markers EpCAM, CK19 and SCGB2A2 alone would not have detected these hormone receptor and HER2-negative cells." (PMID 36831613, 2023). "A unique, nature-inspired, long-circulating nanoparticles containing chemotherapy and imaging agents was developed to target and treat EpCAM+ breast cancer with minimal uptake to non-targeted cells as well as to visualize tumor; hence, treatment progress could be monitored at the same time." (PMID 36235009, 2022). "Therefore, depletion of EpCAM-positive cells from the peripheral blood of breast cancer patients with a non-specific separation method might be able to reduce the probability of metastasis formation." (PMID 32104205, 2020). "Indeed, it has first been noticed that knockdown of EpCAM could inhibit the expression of EMT-transcription factors Snail and Slug in colon cancer and that its overexpression could enhance TGF-β1-induced EMT in MCF-7 breast cancer cells." (PMID 31225512, 2019). "However, the mechanism by which EpCAM promotes the progression of breast cancer is not understood." (PMID 26356670, 2015). "Moreover, >99% of the cells were negative for the epithelial cell adhesion molecule (EpCAM), a breast cancer epithelial cell surface marker; CD31, also known as platelet endothelial cell adhesion molecule (PECAM-1), an endothelial cell marker, and CD45, a pan-leukocyte marker." (PMID 22954256, 2012). "Indeed, the CellSearchTM isolation method, which uses epithelial cell adhesion molecules such as EpCAM to detect such tumour cells, is not able to recognize normal-like breast cancer cells, which, in general, have aggressive features and are negative for the expression of EpCAM." (PMID 22276006, 2009). "For example, in tumours with high EpCAM expression but low or absent EGFR expression, such as the MCF-7 breast cancer cell line, EpCAM-targeted PIT would be a more appropriate therapeutic option." (PMID 40792441, 2025). "While CELLSEARCH® remains the only FDA-approved technology for breast cancer CTC enumeration, its dependence on EpCAM-based sorting means that it invariably misses EpCAM-negative CTCs." (PMID 40867346, 2025).
breast carcinoma (continued). "Similar findings were observed in another two breast cancer cell lines MDA-MB-468 and MCF-7, while the percentage of EpCAM+ fraction was reduced mildly in MDA-MB-468 cells and not even decreased in MCF-7 cells in response to shear stress." (PMID 33143160, 2020). "Analysis of the TCGA breast cancer database shows a highly significant correlation between CD163 or CD68 and SIGLEC9 but not with the epithelial markers, EPCAM or KRT8." (PMID 33149188, 2020). "For spiking experiments, human breast cancer cell lines (high EpCAM-expressing MCF-7 cells and non-EpCAM-expressing Hs-578Tcells) and a low EpCAM-expressing human prostate cancer cell line (PC-3) were used in a buffer." (PMID 31088479, 2019). "Interestingly, also in breast cancer, fewer CTCs have been reported for brain metastatic patients when analyzed by the CellSearch system, and those CTCs that were competent to colonize the brain as a distant target organ site were predominantly EpCAM-negative but EGFR, NOTCH1 and HPSE-positive." (PMID 30572662, 2018). "EpCAM expression was detected only in MCF7 cells and not in MDA-MB-231 cells, therefore the proof of principle of QD transfer from nanoengineered MSCs to breast cancer cells was demonstrated using MCF7 cells only." (PMID 29515946, 2018). "The cell lines selection was base on the consideration of including both EpCAM positive cells (human breast cancer cell MCF-7, human lung cancer cell A549, human colonal cancer cell SW480) and EpCAM negative cells (human cervical caner cell Hela)." (PMID 27935872, 2017). "EPCAM was expressed in both sample types during the 96 h period, and CD227 was expressed in breast-cancer samples, but cMET was not expressed in any of the samples." (PMID 28975085, 2017). "In case of breast cancer cell line (MCF7), there was no significant change in OCT4 and NANOG expression upon silencing EpCAM, while SOX2 was downregulated." (PMID 26176230, 2015). "EpCAM based IE/FACS detected and captured a portion of spiked cells from each of the 10 cell lines representing all breast cancer subtypes, including basal-like but not claudin-low cancers." (PMID 26556851, 2015). "Antibody-mediated receptor crosslinking induced AKT phosphorylation downstream of PI3K in breast cancer cells sorted for absence of CD45 (hematopoietic cell exclusion), expression of EpCAM (cancer cell inclusion), and NKG2D." (PMID 25291178, 2014). "Three genes (KRT19, EpCAM and CEACAM) showed no specificity for breast cancer circulating tumor cells." (PMID 24058517, 2013). "Using these gene markers [mam, CEA, CK19, PIP, muc1, PSE, Erb (BM only) and EpCAM (PBL only)] we analyzed 215 PBL samples and 177 BM samples from patients with T1-T3 primary breast cancer without clinical evidence of metastatic disease." (PMID 18289390, 2008). "The protein expression levels of the two immune checkpoint molecules, CD200R and CD274, were measured as mean fluorescence intensity (MFI) in non-hematopoietic cells, identified by the expression of cytokeratin 18 and CD326 (EpCAM) and dim/negative expression of CD45, from breast cancer biopsies." (PMID 39858472, 2025). "Clusters negative for EPCAM and KRT8, corresponded to the cells of the TME, like endothelial cells (CD31+), immune cells (CD45+) and fibroblasts (COL1A1+) and were present in all breast cancer subtypes." (PMID 36635273, 2023). "In the last, we provided the occurrence of MCT4+PD-L1+EpCAM+ axis in breast cancer differentiation through bc-GenExMiner, revealing that high MCT4+PD-L1+EpCAM+ axis occurs in TNBC status and nodal status, and the change was not obvious in ER-positive, PR-positive, and HER2-positive breast cancer." (PMID 36199799, 2022). "We used an antibody-independent CTC enrichment platform, ApoStream®, which does not rely on any antibody, including anti-EpCAM, to capture EMT- and CSC-CTCs in breast cancer patients who received neoadjuvant chemotherapy and correlated them to pathological complete response (pCR)." (PMID 32214335, 2020).
breast carcinoma (continued). "In addition, EpCAM- and AnxA2-positive exosomes are negative for the expression of calnexin and GM130, respectively, and show the purity of exosomes isolated from breast cancer serum samples." (PMID 31992335, 2020). "Based on those findings and the lack of a priori knowledge of specific surface markers when processing breast cancer liquid biopsies, we sought to use an epitope independent CTC enrichment platform to overcome the limitation in isolating claudin low and/or EpCAM negative cells." (PMID 29467948, 2018). "Interestingly, MET was suggested to contribute to the putative metastasis-initiator circulating cells in breast cancer (e.g. EPCAM+CD44+CD47+MET+ CTCs, but not the bulk EPCAM+ CTCs)." (PMID 28212540, 2017). "We performed real-time-PCR (RT2-PCR) human embryonic stem cell array (Qiagen) profiling to determine the expression of 83 candidate genes in FACS-sorted EpCAM-negative, uPAR+/int β1+ and uPAR−/int β1− stem cell CTC subsets derived from clinically diagnosed breast cancer patient with or without BCBM." (PMID 26631983, 2015). "Next, to prove the tumor origin of DAPI−/CD45−/EpCAM-negative/CD24−/CD44+/uPAR/int β1 cells as putative CTCs, we performed transcriptome analysis of 83 breast cancer candidate genes present in human breast cancer real-time PCR (RT2-PCR) profiler arrays (Qiagen)." (PMID 26631983, 2015). "Notably, in breast cancer, the absence of CD24 combined with the presence of CD44 and EpCAM (CD24−CD44+EpCAM+) appears to be critical for the identification of breast CSCs." (PMID 24955581, 2014). "ISET® may not be the most suitable method for counting CTCs from patients with breast cancer without brain metastases because of its potential failure to identify some cells during EMT and its limited comparability with most other studies (in which EpCAM-based methods have been used)." (PMID 34644733, 2021).
ovarian carcinoma (273 papers, 1994 to 2026). A malignant neoplasm originating from the surface ovarian epithelium. "Overexpression of CD24 and EpCAM in ovarian cancer cells is associated with poor prognosis and drug resistance." (PMID 38796525, 2024). "For instance, Lee and Ahn found that AAV2 modified with a streptavidin-biotin complex linked to an anti-EpCAM antibody exhibited significant efficacy in targeting EpCAM-positive ovarian cancer cells." (PMID 38745236, 2024). "For instance, CD24 and epithelial cell adhesion molecule (EpCAM) were found to be highly expressed in tumor-derived exosomes and were thus associated with ovarian cancer development." (PMID 37215442, 2023). "EpCAM is released on EVs, and EpCAM positive EVs has been associated with different cancer diseases including breast and ovarian cancer." (PMID 35012489, 2022). "The co-expression of EpCAM+CD45+ hybrid cells has already been described in the ascites of ovarian cancer patients, which the authors associate with a maintenance of epithelial features and the gain of pro-migratory characteristics." (PMID 35884505, 2022). "EpCAM has been detected in exosomes isolated from serum of patients with ovarian cancer, which confirmed the presence of diagnostic miRNAs in exosomes." (PMID 36741380, 2022). "EPCAM and Claudin 4 maintain the bicellular tight junction and their alteration is well implicated in ovarian cancer." (PMID 33663405, 2021). "In ovarian cancer, gene promoter methylation and histone modifications were associated with EpCAM expression patterns." (PMID 34209658, 2021). "EPCAM, an epithelia cell localized type I transmembrane glycoprotein, was initially identified as a highly expressed tumor-associated antigen in ovarian cancer." (PMID 33135729, 2020). "EpCAM-siPKCι aptamer-led cell growth reduction in PRKCI-amplified ovarian cancer cells was clearly caused by apoptosis as we detected apparent cleavage of PARP and CASP3 after 3-day treatment in SK-OV-3 and OCC1 but not in the OVCAR-8 cell line." (PMID 32820156, 2020). "Focusing on the complex between EpCAM, claudins and tetraspanins, we described a sequence of events by which of the molecules associate each other in ovarian cancer." (PMID 32091301, 2020). "In our study, both of exosomal ApoE, EpCAM and Plg were detected and verified, and this proved that ovarian cancer tissue associated proteins are expressed on serum EVs and this is the foundation for further investigation of their biomarker potential." (PMID 31718609, 2019). "Immunohistochemical analysis revealed that Bcl-2 expression is detected mainly in EpCAM-positive cancer cells, confirming their association with Bcl-2 expression in ovarian cancer." (PMID 28574829, 2017). "When incubated with autologous tumor-associated T cells and EpCAM+ ovarian cancer cells derived from ascites, MT110 upregulated the expression of T cell activation markers and enhanced its cytoxicity to malignant cells." (PMID 28931402, 2017). "Recently, Taylor and his colleagues reported the presence of diagnostic miRNAs from EpCAM-positive exosomes from ovarian cancer patients’ serum." (PMID 24460816, 2014). "Overexpression of EpCAM has been associated with dismal prognosis in other tumor entities, such as gallbladder cancer, ovarian cancer and pancreatic cancer." (PMID 24380380, 2013). "EpCAM is considered both an epithelial marker and ovarian cancer stem-like cells marker whose expression is associated with poor prognosis in ovarian cancer patients." (PMID 22916288, 2012). "In this study, we set out to unravel the epigenetic marks underlying EpCAM overexpression in ovarian cancer." (PMID 21694727, 2011). "Here, we investigate epigenetic mechanisms and transcription factors underlying the overexpression of EpCAM in ovarian cancer." (PMID 21694727, 2011).
ovarian carcinoma (continued). "The increase of epithelial cell adhesion molecule (EpCAM) concentration is associated with the stages of ovarian cancer, which indicates EpCAM in exosomes could be useful for the diagnosis of ovarian cancer." (PMID 37497408, 2023). "Indeed, Lee and Ahn showed that AAV2 modified with a streptavidin–biotin complex linked to an anti-EpCAM antibody was substantially effective at targeting EpCAM-positive ovarian cancer cells." (PMID 37231038, 2023). "Notably, EPCAM protein expression was associated with stemness, aggressive features and chemoresistance in ovarian cancer." (PMID 34070214, 2021). "The expression of CD117 and CD44, which has been associated with a cancer stem cell phenotype in ovarian cancer, was found in up to 90% of EpCAM+/CD45+ ovarian cancer hybrid cells indicating an association of cell fusion with the origin of cancer stem/initiating cells." (PMID 34503305, 2021). "In addition, high expression of EpCAM in ovarian cancer was associated with tumor recurrence and poor prognosis." (PMID 35582216, 2020). "In addition, significantly increased expression levels of EV-associated CD24, EpCAM, and CA-125 were found in ovarian cancer patients compared to healthy patients." (PMID 31212643, 2019). "CD44, CD24, CD133, CD117, and EPCAM have been reported to be associated with ovarian cancer." (PMID 30581772, 2018). "Given that EpCAM was clinically associated with chemoresistance to platinum-based chemotherapy, we next examined the relevance of chemoresistance in a subpopulation of EpCAM-positive cells in in vitro assays using ovarian cancer cell lines." (PMID 28574829, 2017). "Similarly, a retrospective study found that EpCAM was overexpressed in 68.8% epithelial ovarian cancer (EOC) and was associated with reduced survival time, especially in stage III–IV and poorly differentiated subtype." (PMID 28931402, 2017). "Finally, we also found that an increased expression of EpCAM is associated with poor prognosis in ovarian cancer patients." (PMID 28574829, 2017). "Conversely, EpCAM over-expression has been associated with both improved prognoses and favorable response to platinum based chemotherapy further suggesting that epithelial differentiation leads to improved prognosis in ovarian cancer." (PMID 27253518, 2016). "To further investigate whether a causal relationship exists between EpCAM expression and chemotherapeutic response, we analyzed 52 patients with ovarian cancer who had undergone platinum-based chemotherapy, except for cases achieving complete surgery, defined as no visible residual tumors." (PMID 28574829, 2017). "When ovarian cancer cells were co-incubated with platelets for 24 h, EpCAM mRNA expression decreased (P = 0.0404) while the mRNA expression of the immune checkpoint marker PD-L1 (CD274) increased (P = 0.0174) in cells cloaked with platelets." (PMID 41125825, 2026). "This microfluidic approach was employed for the multiplexed detection of blood-based ovarian cancer from three different exosomal tumor markers, such as CA-125, EpCAM, and CD24." (PMID 40277517, 2025). "sEVs released from ovarian cancer cells, which carry markers such as CD24 and EpCAM, hold potential for use in diagnostic applications." (PMID 40008006, 2025). "Due to the epithelial source of EPCAM, EPCAM+ sEVs have been demonstrated to be more specifically secreted by epithelial tumors, such as pancreatic ductal adenocarcinoma and ovarian cancer." (PMID 41551611, 2025). "Exosome membrane proteins like CD24 and EpCAM can be detected in ascitic fluid from ovarian cancer patients using nano-plasmonic sensors." (PMID 40143147, 2025). "The process involves immunoaffinity capture using anti-EpCAM-coated magnetic microbeads to pre-enrich exosomes from the serum of patients with benign conditions and early-stage ovarian cancer." (PMID 40143147, 2025). "The cancer stem cell markers epithelial cell adhesion molecule (EpCAM) are overexpressed in ovarian cancer." (PMID 40034272, 2025).